CASP8 (caspase 8)
Diseases named in the same sentence as CASP8 in open-access papers (continued):
Sharing a sentence is not in itself a finding about the gene and the disease.
cancer (continued). "As a central player in the initiation of apoptotic cascade, caspase-8 expression or its activity are often reduced in cancer." (PMID 34482382, 2021). "NOV inhibited the expression of AP-1 and JUK and promoted the expression of Caspase-8/3 in cancer tissues in a tumor cell xenotransplantation nude mouse model." (PMID 35201461, 2021). "Recently, TAMs were selectively targeted by the anti-cancer drugs trabectedin (Yondelis®) and lurbinectedin (Zepsyre®), respectively, inducing caspase-8-mediated apoptosis." (PMID 33026575, 2021). "Caspase-8 has therefore a dual role in cancers by modulating both the expression profile in the tumor itself and the re-organization of the TME." (PMID 33026575, 2021). "For instance, in some cancers, including hepatocellular carcinoma, pancreatic carcinoma, caspase-8 was upregulated, compared to normal tissues." (PMID 34482382, 2021). "In certain cancer cells, it has been suggested that caspase-8 sustains tumor survival by regulating the “FADDosome” complex assembly and promoting proinflammatory cytokines secretion." (PMID 34482382, 2021). "Taken together, caspase-8-mediated necroptosis has exhibited a dual effect, either suppressing cancer or promoting cancer, on cancer development in different tissues." (PMID 33665167, 2020). "Previous studies showed that Cos induced cancer cell death via stimulation of caspase-8 or caspase-9, depending on cancer cell types or other factors." (PMID 33194716, 2020). "One recent study demonstrated that sirtuins are able to control RIPK1-caspase 8-induced apoptosis in cancer." (PMID 33282964, 2020). "Instead, caspase 8 localizes to the lamella (the leading part) of migrating cancer cells where it is proposed to help organize protein complexes needed for migration." (PMID 32810419, 2020). "When cancer cells interact with CAFs by death receptor 4, caspase-8 is activated in cancer cells and leads to apoptosis." (PMID 33178597, 2020). "This is consistent with the observation that CASP8 activity is impaired in a variety of cancer types, such as neuroblastoma, medulloblastoma, and HNSCC, through mutations and epigenetic silencing." (PMID 33108350, 2020). "Several recent studies have demonstrated that caspase-8 plays an important role in the promotion of neuroinflammation, T-cell function, and cancer-related inflammation." (PMID 32023953, 2020). "While cancer cells proficient for caspase-8 died by apoptosis, the depletion of caspase 8 promoted necroptosis by stabilizing RIPK1." (PMID 32231206, 2020). "TLR3-mediated mechanism of apoptosis in cancer cells is dependent on caspase-8 activation, which activates caspase-3 by proteolytic cleavage to amplify caspase-8 apoptosis initiation signals." (PMID 32093313, 2020). "β-sitosterol, a phytosterol isolated from methanolic extract of Eclipta alba was reported to possess antioxidant as well anticancer property, and induce apoptosis via caspase 8-dependent pathways in cancer cells." (PMID 33225921, 2020). "Inhibition of CASP8 has been reported to sensitize cancer cells to necroptosis, a regulated cell death mechanism." (PMID 33108350, 2020). "β-Sitosterol induces apoptosis mediated by caspase-8 activity and by modulation of the estrogen receptor (ER), which inhibits the proliferation of sensitive cancer cells such as MCF7." (PMID 32023823, 2020). "We found that PFL decreased various integrins as well as EGFR in cancer cells by promoting internalization and autophagic degradation of these molecules, subsequently inducing caspase-8 dependent cell apoptosis." (PMID 31052260, 2019).
cancer (continued). "Danazol induced the arrest of MDR cancer cells at the G2/M phase and caspase-8–related early apoptosis." (PMID 31406162, 2019). "Treatment with the fraction increased the expression of Bax, caspase-9, active caspase-3, caspase-8, LC-3, and beclin-1 and decreased the expression of Bcl-2, caspase-3, and pro-caspase-8 in cancer cells." (PMID 31534620, 2019). "TRAIL resistance in some cancer cells involves abnormal function of the death-inducing signaling complex (DISC) due to inactivation or downregulation of caspase-8 or inhibition of DISC by c-FLIP." (PMID 31013630, 2019). "The fact that SKE increased the sub-G0/G1 cell population and enhanced caspase-8 initiator activity supports the notion that it activated the extrinsic apoptosis pathway in the MCF-7 cancer cell line." (PMID 31096565, 2019). "CASP8 is a member of the caspase-cysteine protease family and plays an important role in the development of cancer." (PMID 31905767, 2019). "Following incubation with 9F7-F11, cancer cell apoptosis occurs through activation of caspase-8, − 9 and − 3 and the subsequent cleavage of poly (ADP-ribose) polymerase (PARP)." (PMID 31443721, 2019). "Based on this figure, activation of caspase 9 was higher than caspase 8 in both types of cancer cells." (PMID 30728391, 2019). "Apoptosis of SDBS KD cells in a stiff matrix was significantly inhibited by the caspase 8 inhibitor, indicating that activation of the caspase 8 pathway by SDBS KD is critical for cancer cell apoptosis in stiff matrices." (PMID 31853379, 2019). "Others, such as FN1, EP300, CASP8, EGF and MAP2K1, which were associated with the pathways involved in cancer, were also hub-node genes." (PMID 31501464, 2019). "A comparison of CASP8-MT HNSCs and CASP8-MT UCECs highlighted similarities and differences between the two carcinomas." (PMID 30775178, 2019). "The genes that contributed to core enrichment in these gene sets in CASP8-MT UCECs also contributed to core enrichment of the same gene sets in CASP8-MT HNSCs, indicating that similar immune response genes were upregulated in the two carcinomas." (PMID 30775178, 2019). "Similar to our results, other reports have shown that proteasome inhibitors, including MG132, induce caspase-8-mediated apoptosis in various cancer cell lines." (PMID 30322167, 2018). "Caspase-8 is a member of the caspase cysteine protease family and plays an important role in cancer development." (PMID 29423041, 2018). "The percentage of neurons containing CASP3 within MPs located close to cancer-affected regions of the stomach was higher, while containing CASP8 was lower compared to the unchanged regions." (PMID 30019295, 2018). "Active caspase-9 and active caspase-8 were also present in the treated cancer cells, though the numbers of cells positive to caspase-9 detection were significantly higher than those that were positive to caspase-8." (PMID 30304821, 2018). "While for extrinsic pathway exposure to anti-cancer drugs will intervene with the cell surface of the death receptor which activates caspase 8 and subsequently activates the effector caspase." (PMID 29303982, 2018). "Standard chemotherapy regimens promote DNA damage and are typically thought to rely on the canonical apoptotic activity of Caspase-8 and on apoptosis for the elimination of cancer cells." (PMID 30501030, 2018). "Accordingly, it has recently been shown that UHRF1 down-regulation in cancer cells induced caspase-8 dependent apoptosis and the activation of caspase-3." (PMID 29983883, 2018). "Expression of caspase-3 and caspase-8 were elevated after treatment by fractions G, I, and J in both cancer cell lines HeLa and MDA-MB-231." (PMID 29881421, 2018). "This is in agreement with the observation that Caspase-8 expression or its enzymatic activity, required for the execution of the apoptotic signal, are often impaired in cancer." (PMID 30501030, 2018).
cancer (continued). "Treatment of cancer cells with the latest fraction increased expression of caspase-3 and caspase-8 demonstrating induction of apoptosis as possible mechanism of action." (PMID 29881421, 2018). "Fas ligand (FasL) and tumor necrosis factor-related apoptosis-inducing ligand (TRAIL) provide a death signal via the extrinsic apoptotic pathway, activating caspase-8 in cancer cells." (PMID 29876007, 2018). "Our recent work demonstrates that DR5 suppression promotes cancer cell invasion and metastasis through caspase-8/TRAF2-mediated activation of ERK and JNK signaling and MMP1 elevation." (PMID 28482915, 2017). "On the light of the pro-apoptotic effects induced by miR-34a transfection combined with anti-cancer drugs treatment, we evaluated the proteolytic processing of both initiator (Caspase-8 and -9) and executioner caspases (Caspase-3 and -7)." (PMID 29263373, 2017). "The observation that Caspase-8 is retained in many tumors (reviewed in [Stupack, 2013]) suggests a dual role for Caspase-8 in cancer." (PMID 28594322, 2017). "Future studies are now needed to understand why Caspase-8 promotes cell death in some cancers but the formation of new blood vessels in others." (PMID 28594322, 2017). "When autophagy is inhibited, caspase 8 dependent cell death is paralleled by the increase of p62 in cancer cells." (PMID 28159921, 2017). "c-FLIP has been shown to be a key negative regulator of extrinsic apoptosis by inhibiting the activation of caspase-8 in human cancer cells." (PMID 28035061, 2017). "To further figure out the anti-cancer mechanism of celecoxib and curcumol, we examined the activation of caspase-8, -9 and -3." (PMID 29383179, 2017). "In most cancer cells, a limited amount of activated caspase-8 is produced, which is insufficient to directly cleave and activate caspase-3." (PMID 28270124, 2017). "Par-4 secreted by normal and cancer cells bound selectively to a receptor GRP78 on the cancer cell surface, where it induced apoptosis by a caspase-8/caspase-3-dependent pathway." (PMID 28076793, 2017). "In spleen cells of that study, cancer-related gene Cdkn2a was found up-regulated by spaceflight, while Birc5, Casp8, Ctnnb1, Map2k1, Mdm2, Nfkb1, and Pdgfa showed less expression." (PMID 28701719, 2017). "These inhibitory effects on IAP proteins by SMAC mimetics leads to TNFα-triggered activation of caspase-8 and caspas-3 cascade and thus inducing apoptosis in cancer cells which secrete TNFα in an autocrine fashion." (PMID 28460471, 2017). "For example, we have previously demonstrated in several cancers including NSCLC that downregulating FLIP enhances chemotherapy-induced apoptosis in a caspase-8 dependent manner, whereas overexpression of FLIP blocks caspase-8-mediated apoptosis." (PMID 28904817, 2017). "Regarding the roles of caspase-3/8/9 in cancer, impaired expression of caspase-8 and caspase-3 can promote tumor formation and progression and treatment resistance in several types of cancer, including oral cancer." (PMID 28700659, 2017). "Our investigation indicated that compound 3c effectively inhibited cancer cells growth at the low concentration and subsequently led the cells to enter the apoptotic pathway which was indicated by cleavage of caspase 9, caspase 8, caspase 3 and PARP." (PMID 27625151, 2016). "The activation of caspase-8 and -9 both act to commit the cancer cells to apoptosis through downstream caspase-3/7 activation, PARP cleavage and the lack of NFkB translocation into the nucleus." (PMID 27070314, 2016). "Cancer cells that detach from the substrate can avoid anoikis by downregulating caspase 8 via promoter methylation." (PMID 27929432, 2016).
cancer (continued). "Cellular FLICE-like inhibitory protein (cFLIP) plays one of the most important roles in preventing caspase-8 activation as an anti-apoptotic regulator in cancer cells." (PMID 28025559, 2016). "Several proteases such as members of the ADAMTS family, caspase 8 and trypsinogen IV are epigenetically silenced in cancer cells." (PMID 27388476, 2016). "We have shown elsewhere that it triggers the intrinsic mitochondrial-mediated apoptotic pathway in HT29 colon-cancer cells, and in this paper that it triggers the extrinsic caspase-8-mediated apoptotic pathway in Caco-2 colon-cancer cells." (PMID 26751572, 2016). "Killing by FasL occurred slowly, requiring transient, often multiple NK-cancer cell conjugations that gradually activated caspase-8, while lytic granule triggered rapid cytotoxicity by a switch-like induction of granzyme-B upon a single, prolonged conjugation." (PMID 27323411, 2016). "We found that DZNep increased cancer cell sensitivity to TRAIL signaling by promoting caspase-8 processing through accelerated cFLIP degradation." (PMID 25738497, 2015). "In contrast, the role of caspase-8, apart from its involvement in certain amplification loops, has been seriously questioned, particularly in regard to melanoma cancer cells." (PMID 25685064, 2015). "Through genetic manipulation of DR5 expression in human cancer cells, we have shown that DR5 does indeed function as a suppressor of cancer invasion and metastasis, primarily via modulating caspase-8/TRAF2-mediated signaling." (PMID 26510914, 2015). "P-ERK is known to protect cancer cells from undergoing death receptor-mediated apoptosis by phosphorylating pro-caspase-8." (PMID 26036637, 2015). "Contrary to c-FLIP, however, caspase-8 was still recruited at 42 °C, consistent with the gain of pro-apoptotic function afforded by short incubation of the cancer cells at 42 °C in the presence of TRAIL." (PMID 25675293, 2015). "Studies have shown that with exogenous stimulation, the expression of caspase-3, caspase-8 and caspase-9 in in vitro cultured cancer cells were increased." (PMID 25951128, 2015). "It has been also reported that JNK activation up-regulates DR5 expression, which leads to apoptosis in cancer cells through caspase-8 activation." (PMID 25883904, 2015). "In conclusion, the pretreatment of EGFR tyrosine kinase inhibitors promote pro-caspase-8 dimerization that sensitizes cancer cells to DNA-damaging agents." (PMID 26036637, 2015). "The impaired expression and function of caspase 8 promotes tumour formation, progression and treatment resistance in several types of cancers." (PMID 26390405, 2015). "A549 and PC-9 cancer cells treated with two compounds in combination showed significant increase in caspase-9 and caspase-8 activities." (PMID 25799586, 2015). "H2O2 can specifically oxidize and activate the intrinsic apoptosis pathway (i.e., reduce the mitochondrial membrane potential, inhibit expression of Bcl-2, and activate caspase-8 and caspase-3, and therefore inducing apoptosis in cancer cells." (PMID 26330167, 2015). "Noteworthy, compound 2 not only is the best binder for caspase 8, but together with compound 3, it is also the most effective compound in sensitizing Jurkat cancer cell line to TRAIL-induced cell death." (PMID 25962125, 2015). "The role of caspase-8 in various types of cancer cells after taxane treatment has been previously discussed in several reports." (PMID 25685064, 2015). "Small molecules that can activate caspase 8 and/or sensitize resistant cells to death ligands-induced cell death have the potential to become an exciting class of novel pro-apoptotic cancer therapies." (PMID 25962125, 2015). "Our data suggest that pre-treatment with erlotinib can increase the pro-caspase-8 homodimer and thereby sensitize cancer cells to strong apoptotic stimuli, such as doxorubicin." (PMID 26036637, 2015).
cancer (continued). "DAVID ontology analysis revealed enrichment of cancer-associated pathways, including the well-characterized cancer genes MTOR, EGFR, AKT1, and CASP8 in the region of overlap." (PMID 25294808, 2014). "Especially, inactivation of the caspase-8, Fas and DR4/TRAIL-R1 genes either by DNA methylation or mutation as part of the malignant process have been detected in cancer cells, and are thought to contribute to carcinogenesis." (PMID 24618889, 2014). "The apoptotic effectors such as caspase 8, caspase 9 and caspase 3 were found to be upregulated besides DNA repair-associated enzyme, that is, PARP cleavage caused cancer cell death." (PMID 25299784, 2014). "We have recently reported that Ginsenoside Rh2 (G-Rh2) induces the activation of two initiator caspases, caspase-8 and caspase-9 in human cancer cells." (PMID 24622841, 2014). "Fas ligand (FasL) and tumor necrosis factor (TNF)-related apoptosis-inducing ligand (TRAIL) can provide a death signal via the ‘extrinsic’ apoptotic pathway, activating caspase-8 in cancer cells." (PMID 25333266, 2014). "A comprehensive understanding of the overall transcriptional regulation of CASP8 will provide insight into the mechanisms that contribute to the etiology of cancers and their responses to treatment." (PMID 24819879, 2014). "Lack or low caspase-8 expression has also been reported in a number of other cancer types including osteosarcoma and squamous cell carcinoma of the tongue." (PMID 25157404, 2014). "TNF-Related Apoptosis Inducing Ligand (TRAIL) binds to and activates death receptors to stimulate caspase-8 and apoptosis with higher efficiency in cancer than normal cells but the development of apoptosis resistance has limited its clinical efficacy." (PMID 24147007, 2013). "ATM and CASP8 disproportionately increase in relative instability (compared to the other 48 genes in the deletion-prone cancer gene group) as the fraction of deletions ≤50 bp was increased." (PMID 23755193, 2013). "A simplified model of DISC clustering elucidates the mechanism of increased active caspase 8 generation and type 1 activation in cancer cells having increased sensitivity to death receptor activation." (PMID 24709706, 2013). "In our previous studies, we demonstrated that caspase-2 was significantly activated (up to 20-fold) along with other caspases (caspase-3, caspase-9 and caspase-8) during apoptosis induction by taxanes in some cancer cells." (PMID 23672670, 2013). "On the other hand, the elevation in the activity of caspase-8 observed in the present study suggests the apoptosis of cancer cells induced by ICD-85." (PMID 24250584, 2013). "In some cancer cells activated caspase-8 is sufficient to trigger apoptosis, while other cells require activation of the mitochondrial (intrinsic) pathway to amplify the apoptotic signal." (PMID 23573148, 2013). "The tumor suppressor CYLD encodes for a deubiquitinase that plays a critical role in the regulation of NF-κB and activation of caspase-8, its activation being regarded as a therapeutic target in the treatment of cancers." (PMID 23702334, 2013). "These included sites in genes that encode caspases (CASP8 and CASP10) and the von Hippel-Lindau (VHL) tumor suppressor, which have been implicated in various cancers." (PMID 24183664, 2013). "PPD and MβCD modulate lipid raft-dependent signaling pathways including IGF-1R, pAkt, PARP, Caspase-8 and Bid in two different cancer cells." (PMID 23889969, 2013). "We demonstrate that increased sensitivity to death receptor activation in certain cancer cells can allow selective targeting of those cells (such as by death ligands) resulting in selective activation of caspase 8 in only those cells." (PMID 24709706, 2013).